MYC (MYC proto-oncogene, bHLH transcription factor)
Diseases named in the same sentence as MYC in open-access papers (continued):
Sharing a sentence is not in itself a finding about the gene and the disease.
colorectal cancer (continued). "Treatment of these compounds inhibits MYC-dependent transactivation in colorectal cancer cells but not in stem cells or normal colon epithelial cells, and this effect is associated with the role of HUWE1 inhibition in stabilizing Miz1 and Miz1-mediated suppression of MYC target genes." (PMID 34178666, 2021). "It was demonstrated that miR-185 could suppress Wnt/β-catenin signalling and modulate the transcription and translation levels of downstream molecules of this pathway, including MYC and CCND1, in human colorectal cancer, thus exerting tumour suppressor effects." (PMID 32366240, 2020). "Consequently, the usage of inhibitors of the protein–protein interaction of MYC and NMYC with MAX is a possible treatment strategy for both neuroendocrine- and AC-derived colorectal cancer cell lines that harbor a subpopulation with potential stem-like properties." (PMID 32927768, 2020). "Through the validation of differential gene expression in the GEPIA database, we found that the validation of MYC and STAT3 in the GEPIA database yielded the same results as the GEO database, which could be able to serve as targets to play a role as tumor marker in colorectal cancer." (PMID 39830506, 2024). "However, analysis of A375 melanoma cells after treatment with palbociclib revealed significant downregulation of MYC target genes, and no change in mTOR signalling or c-MYC protein, suggesting that the mechanism in melanoma cells is distinct from colorectal cancer cells." (PMID 33572972, 2021). "Unlike prior studies in prostate or colorectal cancers, where miR-32-5p targets BMP5 or PTEN, our work proposes c-MYC as a potential downstream effector in MCF-7 cells, offering a novel therapeutic axis." (PMID 40711670, 2025). "We have shown that a low concentration of dioclofenac (0.1 mM) negatively affected the c-MYC expression in LS174T and LoVo colorectal cancer cells, but not in A549 lung cancer cells." (PMID 38229111, 2024). "However, it is not yet clear how MYC and NCAPG2 are involved in colorectal cancer." (PMID 38637125, 2024).
lung carcinoma (576 papers, 2001 to 2026). "Through GSEA, we found that high‐level expression of POLRMT was linked to MYC targets and Wnt/beta‐catenin signaling, both of which had a role in lung cancer cell processes and proliferation." (PMID 37283308, 2023). "We showed a strong molecular association between USP13 and c-MYC, leading to the upregulation of squamous programs in murine and human lung cancer cells." (PMID 38093367, 2023). "For instance, two focal amplifications of SEs located on the 3’ side of MYC in endometrial carcinoma and lung cancer are close to the MYC promoter region and are associated with aberrant expression of MYC77." (PMID 36720920, 2023). "In the present study, we showed that the loss of UBQLN1 drives tumorigenesis and lung cancer metastasis, which was associated with an increase in MYC expression, cell cycle progression, and EMT." (PMID 37444499, 2023). "Reportedly, SPP1 plays an important role in mediating macrophage polarization and facilitating immune escape in lung cancer, and MYC is an oncogene encoding a transcription factor and participating in multiple metabolic pathways that induce cancer progression." (PMID 36091047, 2022). "Publicly available datasets had indicated a correlation between deletion or truncating mutations of several members of the proximal MYC network and tumor progression in lung cancer." (PMID 34236315, 2021). "Immunohistochemical analysis revealed that USP37 is upregulated in 64% of human lung cancer tissues and is associated with c-MYC expression." (PMID 34758854, 2021). "The E2F-targets and MYC-targets pathways, which have been demonstrated to be associated with the relapse and cell proliferation in lung cancer, enriched in the groups with survival disadvantage." (PMID 34122500, 2021). "The oncoprotein c-MYC (deregulation of the c-Myc protein is associated with cancer progression, including in lung cancer) is strongly linked to poor patient survival and is stabilized by USP28." (PMID 34502538, 2021). "A recent study on lung cancer demonstrated that the loss of the central clock components led to increased c-MYC expression, which enhanced proliferation." (PMID 34285836, 2021). "Among them, TNF had the greatest degree in the HCT-major hub genes-disease network, while IL-6, JUN, EGFR, and MYC were shown to associate with the survival of lung cancer patients." (PMID 32595734, 2020). "The most frequently mutated proto-oncogenes in lung cancer are those from the MYC, RAS, and HER families." (PMID 32604993, 2020). "Other studies showed that miRNA-145 expression reduced in lung cancer cells, causing elevated c-MYC, NUDT1, OCT4 and EGFR expression, increased tumor cell proliferation, metastasis and migration." (PMID 31554377, 2019). "Copy number gain of oncogenes including EGFR, KRAS and c-MYC has been reported in lung carcinoma, where it was associated with advanced stage and poor clinical outcome." (PMID 28501852, 2017). "These authors also found a strong association between c-MYC and H19 transcript levels, in both primary breast and lung cancer patient material." (PMID 25593996, 2014). "Although characteristic patterns of DNA changes are caused by exogenous mutagens in both lung cancer types for several molecular genetic changes, such as G-protein pathways and MYC genes, differences between SCC and SCLC have been shown." (PMID 12107845, 2002). "c-MYC expression is associated with increased in- and reduced e-flux of cholesterol in lung cancer." (PMID 37705742, 2023). "In this study, we revealed the association between HNRNPK and MYC signaling pathway in lung cancer." (PMID 36681772, 2023).
lung carcinoma (continued). "In addition, MYC (associated circRNAs: hsa_circ_0002588, hsa_circ_0007909, hsa_circ_0008604), the well-known metastasis gene for lung cancer, was also identified." (PMID 35123506, 2022). "Nevertheless, we confirmed that MYC amplification is a frequent event in lung cancer patients and may have high potential in clinical diagnostics for patient selection regarding personalized therapies." (PMID 33014186, 2020). "IL-6, JUN, EGFR, and MYC were shown to associate with the survival of lung cancer patients." (PMID 32595734, 2020). "Since the risk allele rs6983267 G has been shown to have a stronger affinity to TCF7L2 and may induce enhanced MYC expression, rs6983267 might be associated with survival in patients with lung cancer." (PMID 22848662, 2012). "Our results indicate that specific cytogenetic alterations present in preinvasive lung lesions such as amplification or over-representation of the TP63 and MYC genes are highly associated with the diagnosis of lung cancer and therefore suggest a role of those markers in assessing lung cancer risk." (PMID 19547694, 2009). "Intriguingly, in addition to MYC amplification, we identified multiple distinct CNVs that varied between the two groups, including arm 20q gain and arm 2q loss, which may contribute to the metastasis of lung cancer." (PMID 39744567, 2025). "However, we recently showed that the purified Omomyc miniprotein displays cell-penetrating properties and has the innate capacity to enter NSCLC cells, reach their nuclei and interfere with MYC transcriptional activity, causing a therapeutic impact in mouse models of lung cancer." (PMID 36860495, 2022). "Interestingly, inactivation of chromatin modifier p300, a homolog of the histone acetyltransferase CREBBP, has been associated with deregulation of MYC transcription in lung cancer cell lines, and loss of MYC expression in the context of CREBBP and EP300 loss is synthetically lethal." (PMID 31097695, 2019). "Via the GR, GCs suppress ERK signaling and downregulate cyclin D/E2F/MYC while inducing p21/p27, leading to G1 arrest and senescence in lung cancer models." (PMID 40868244, 2025). "Collectively, higher CIP2A expression followed by RING1 reduction in lung cancer cells increases cell proliferation by c‐MYC and Cyclin B1 upregulation through inhibition of PP2A activity." (PMID 41362702, 2025). "In line with our findings, previous studies showed higher MYC amplification in CNSm of lung cancer compared to primary lung cancer." (PMID 40883281, 2025). "Experimental evidence has shown that MYC contributes to lung cancer progression through multiple signaling pathways, including the Wnt and PI3K/AKT pathways." (PMID 41241099, 2025). "In a panel of human lung cancer biopsies, multiplexed immunofluorescence staining validated that Notch activation negatively correlated with MYC expression in TECs." (PMID 40303332, 2025). "Conversely, hyperoxic environments inhibit lung cancer growth and invasiveness by suppressing the MYC/MCT1 axis, leading to intracellular lactate accumulation and acidification." (PMID 40166469, 2025). "FOSL1 and MYC are oncogenic transcription factors that contribute to the development and progression of various cancer types, including lung cancer, and their expression levels have been shown to be upregulated by the EGFR-ERK1/2 signaling pathway." (PMID 39858622, 2025). "Knockdown of RING1 increased lung cancer cell proliferation and migration in vitro and in vivo, linked to the upregulation of CIP2A and its downstream molecules, c‐MYC and Cyclin B1." (PMID 41362702, 2025). "Excessive activation of the MYC gene by amplification can be observed in breast, pancreatic or lung cancer, while its aberrant influence on signaling pathways such as PI3K/AKT or MAPK is typical of glioblastoma and colon cancer." (PMID 39858030, 2025).
lung carcinoma (continued). "In immunocompetent C57BL/6J mice, Lewis lung carcinoma (LLC) cells mouse lung cancer xenograft model, the overexpression of MYC significantly accelerated tumor proliferation." (PMID 39899538, 2025). "In contrast, for H460 lung cancer cells, MYC transcription was similar to that in normal lung cells; however, the c-Myc protein level was reduced nearly to undetectable levels." (PMID 40226330, 2025). "In this study, we showed that CIP2A functions as an oncogene in lung cancer that upregulated the c‐MYC and Cyclin B1." (PMID 41362702, 2025). "The study reported LRRC45 facilitate lung cancer progression through the upregulation of c-MYC and several other proteins." (PMID 41458604, 2025). "Bidirectional co-immunoprecipitation (Co-IP) assays confirmed a physical interaction between RPL35A and MYC in lung cancer cells." (PMID 41241099, 2025). "It was also found that RING1 KD promotes lung cancer cell proliferation by upregulating CIP2A expression followed by increase of c‐MYC, and Cyclin B1." (PMID 41362702, 2025). "LPCAT1 has been shown to significantly promote brain metastases of lung cancer by upregulating the PI3K/AKT/MYC pathway, making it a promising target for treating BM in lung cancer patients." (PMID 38589859, 2024). "Lung cancer induction dramatically activated c-MYC and MMP9 gene expression by about 161 and 64% compared to those of the negative control group." (PMID 39338293, 2024). "MYC overexpression induces PD-L1 mRNA and protein expression in prostate, breast, colon, and lung cancers; PD-L1 mRNA expression is decreased proportionally to MYC protein inactivation." (PMID 37450923, 2024). "Co-expression of MYBL1 and MYC are detected in pharynx cancers, adenoid cystic carcinoma and breast, ovarian and lung cancers." (PMID 38473786, 2024). "This is consistent with previous reports of mutations in lung cancer fitness, and it reflects the higher incidence of mutations such as KEAP1, NFE2L2, EGFR, and MYC." (PMID 38459554, 2024). "MRT-2359 is an effective oral G1 to S phase transition 1 (GSPT1) degrader that indirectly targets MYC with preferential antiproliferative activity against MYC-driven lung cancer." (PMID 39723215, 2024). "For example, FUBP1 can be recruited to c-MYC FUSE through lncRNA binding, resulting in the activation of c-MYC transcription and facilitating the proliferation, survival, invasion, and metastasis of lung cancer cells." (PMID 38443680, 2024). "Another single‐cell study found that in xenograft models of chemotherapy‐resistant non‐small cell lung cancer, there is an upregulation of MYC target genes and c‐MYC protein." (PMID 39350478, 2024). "USP37 stabilizes MYC in lung cancer and the oncogenic fusion protein PLZF/RARA in Acute promyelocytic leukaemia (APL)." (PMID 37118828, 2023). "In this study, MYC was amplified in 51% of the lung cancer cases, verifying our former results (43% sensitivity and 99% specificity) in an independent study group." (PMID 37858127, 2023). "In contrast to TERT the published percentages for amplification of MYC in lung cancer vary more, ranging from 11% to 88%." (PMID 37858127, 2023). "Complementarily, a potential role of MYC expression in the context of RAS pathway targeted therapies has been suggested by recent clinical data reporting MYC amplification in lung cancer tumors resistant to Sotorasib50." (PMID 37816716, 2023). "USP37 has been found to regulate the turnover of c-MYC in lung carcinoma by direct physical interaction." (PMID 36985413, 2023). "This is supported by previous findings that niclosamide dysregulates MYC in oral squamous cell carcinoma and lung cancer." (PMID 36735625, 2023). "The findings from the present study suggest that MYC can be a potential target in lung cancer with underexpressed UBQLNs." (PMID 37444499, 2023). "Although emerging studies have revealed the important functions of HNRNPK and MYC in cancer, limited evidence were supported in lung cancer." (PMID 36681772, 2023).
lung carcinoma (continued). "In humans, MYC has been reported to be predominantly in the cytoplasm in the normal basal cells of the airways of patients with lung cancer, but cytoplasmic MYC is transferred into the nuclei of premalignant lesions and squamous cells." (PMID 38093367, 2023). "Similar enrichments of SGMs were seen in other core TSGs such as RB1, NF1, and ARID1A and emerging TSGs such as MGA, a transcription factor of the MYC network that suppresses growth and invasion in cellular and mouse models of lung cancer." (PMID 37922356, 2023). "KRT6A regulates the pentose phosphate pathway through the MYC pathway, thereby promoting lung cancer cell growth and invasion." (PMID 37315289, 2023). "All these results suggested that HNRNPK plays important functions in lung cancer by perturbing the MYC signaling pathway." (PMID 36681772, 2023). "Another study in lung cancer suggested that USP37 has been shown to directly deubiquitinate MYC and block its degradation, and MYC expression has been associated with poor patient prognosis in osteosarcoma." (PMID 37118828, 2023). "Our functional studies overexpressing MYC in KRASG12C lung cancer cells support an active role as a resistance mechanism to KRASi." (PMID 37816716, 2023). "Among them, C‐MYC (further called MYC) has the strongest oncogenic potential and is widely deregulated in cancer, while N‐MYC and L‐MYC are mainly involved in neuroblastoma and lung cancer, respectively." (PMID 37519063, 2023). "MiR-34a-5p/miR-34c-5p/miR-302b-3p —LEF1—CCND1/WNT1/MYC axismay be a key mechanism in inhibition of lung cancer metastasis." (PMID 37191432, 2023). "We demonstrated that HNRNPK functions as an oncogene in lung cancer by binding MYC mRNAs to promote the cancer development and progression." (PMID 36681772, 2023). "In colon carcinoma and lung cancer, c-MYC expression is maintained by USP28 and USP37, respectively." (PMID 36985413, 2023). "Mechanistic investigations further demonstrate that HNRNPK promotes tumorigenesis and progression by directly binding to MYC and perturbed the MYC targets pathway in lung cancer." (PMID 36681772, 2023). "Aberrant increased MYC expression has been reported in many human cancers including colon, breast, and lung cancer even though it has an extremely short half-life (∼30 min)." (PMID 37444499, 2023). "Despite the general discrimination between lung cancer and normal tissue MYC and TERT CNV are appropriate to distinguish between each histological subtype and normal tissue, but not to discriminate LUAD from LSCC." (PMID 37858127, 2023). "In response to taxol, MYC up-regulates expression of pro-apoptotic genes to induce cell death of breast, colon, ovarian, and lung cancer cells." (PMID 37345125, 2023). "High MYC expression has been proven to be associated with tumor progression and poor survival, and the MYC status determines the tumor immunophenotype in lung cancer." (PMID 35372012, 2022). "One such instance is the diverse effect of MYC on glutamine metabolism, wherein MYC induces glutamine synthesis in liver cancer but drives glutamine catabolism in lung cancer." (PMID 36618350, 2022). "Unfortunately, developing therapy approaches to target MYC have failed in the past, and new MYC inhibition strategies are far away from clinical implication, although they have been evaluated for the therapy of lung cancer." (PMID 36428670, 2022). "MYC deregulation has been proven to accelerate oncogenesis and program stroma to induce immune suppression in lung cancer." (PMID 36060239, 2022). "Combining HDAC inhibitors and DNA hypomethylating agents further reduced proliferation of lung cancer cells by decreasing MYC levels and reversing immune evasion." (PMID 35351824, 2022). "MYC is an oncogene that is out of control in human cancers, including lung cancer, where it supports oncogenic processes and progression." (PMID 36311939, 2022).